KLK4 (kallikrein related peptidase 4)
Diseases named in the same sentence as KLK4 in open-access papers (continued):
Sharing a sentence is not in itself a finding about the gene and the disease.
tumor (continued). "A high level of KLK4 is expressed by ascitic EOC cells compared to matched primary tumor cells, further supporting its role in the ascitic microenvironment." (PMID 23451143, 2013). "Therefore, we infer that PANDAR regulates KLK4 through miR-367 to affect tumour apoptosis and metastasis." (PMID 34476001, 2021). "Moreover, silencing of KLK4 expression decreased the proliferation and migration and increased apoptosis in EC cells, suggesting that KLK4 functions as a tumor promoter in EC." (PMID 34561425, 2021). "Our analyses suggest that this response may be driven by the metabolic changes observed in KLK4 cells in tumor, namely the production of fatty acids." (PMID 34936871, 2021). "Both PC3-PSMA/Vec and /KLK4 cells had the same baseline bioluminescence, as demonstrated by in vitro imaging of the cell lines prior to injection, confirming the difference in in vivo tumor bioluminescence is indeed due to a difference in tumor burden." (PMID 33255452, 2020). "The finding that KLK4 exhibits anti-tumor effects in vivo has significant translational impact." (PMID 33255452, 2020). "Thus, KLK4 not only reduced the incidence and size of mandible tumors but also limited the degree of tumor-induced bone lysis." (PMID 33255452, 2020). "The anti-tumor effects associated with KLK4 were also observed in the hind legs, where 16% (four of 24, from twelve mice) of hind legs from mice injected with PC3-PSMA/KLK4 had detectable tumors, in contrast to 50% (12 of 24) with the PC3-PSMA/Vec group." (PMID 33255452, 2020). "Moreover, KLK4 was reported to exert its tumor biological effects through activating multiple secreted growth factors like insulin-like growth factor (IGF), hepatocyte growth factor/scatter factor (HGFSF) and transforming growth factor (TGF-β)." (PMID 30811511, 2019). "All in all, LINC01314 over-expression or KLK4 silencing could reduce the MVD of tumor in nude mice with GC." (PMID 31007611, 2019). "Also, in response to over-expression of LINC01314 or silencing of KLK4, tumor weight and the MVD of transplanted tumors were reduced and angiogenesis was suppressed, which was indicated by down-regulated positive expression of VEGF-C and VEGFR-3." (PMID 31007611, 2019). "KLK4 has been shown to increase the activation of plasmin via activation of urokinase plasminogen activator (uPA) which helps with angiogenesis, invasion, and metastasis of the tumor." (PMID 29707153, 2018). "Interestingly, atypical foci of cells occasionally interspersed within tumour‐adjacent normal glands also showed strong KLK4 immunostaining (closed arrows), in comparison with the weak or negligible staining in surrounding normal cells." (PMID 28510269, 2017). "Additionally, our data also revealed miR-422a acted as a tumor suppressor on NSCLC by directly targeting KLK4." (PMID 28177876, 2017). "In addition, KLK4 has been shown to increase the activation of plasmin via the activation of the urokinase plasminogen activator, which helps with the angiogenesis, invasion, and metastasis of the tumor." (PMID 35627227, 2022). "However, we have also shown that KLK4-overexpressing cells exhibit a slower proliferative rate, suggesting that KLK4 may have tumor limiting properties." (PMID 33255452, 2020). "Secondly, and more importantly, it will also open the way for future investigations to understand the mechanisms underlying the negative impact of KLK4 expression/activity on advanced PCa tumor growth and metastasis formation in order to identify novel possible targets." (PMID 33255452, 2020). "KLK4 may, for example, affect ECM remodeling by modulating the tumor-associated urokinase-type plasminogen activator (uPA) / urokinase-type plasminogen activator receptor (uPAR) system activity, i.e. by activation of the pro-form of uPA or cleaving its receptor uPAR." (PMID 30811511, 2019). "Therefore, KLK4 may play a similar role like other KLKs in promoting tumor invasiveness and metastasis." (PMID 30811511, 2019).
tumor (continued). "Shall elevated sodium concentration or/and microenvironment pH be able to inhibit KLK4 ability to clean the ECM barrier and constrain tumor cell migration?" (PMID 36814474, 2023). "The novelty of the current study lies in the fact that we tried to modulate the genes KLK2, KLK4, KLK6, and KLK14 to inhibit the progression of PCa via miR-378, which can be produced in tumor cells through EPA, stimulating co-expression of the gene PGC-1β." (PMID 35681793, 2022). "Another pathway that both PSA and KLK4 have been suggested to regulate is the transforming growth factor (TGF)β pathway which is known to have both pro- and anti-tumor effects." (PMID 33255452, 2020). "Three weeks post-tumor implantation, mice were euthanized and the post-necropsy weight of PC3-PSMA/KLK4 tumors was significantly lower than PC3-PSMA/Vec tumors." (PMID 33255452, 2020). "The incidence of mandible tumors at four weeks was 25% (3/12) for mice injected with PC3-PMSA/KLK4 cells, in contrast to 83% (10/12) for PC3-PMSA/Vec tumor cells." (PMID 33255452, 2020). "Compared to the blank group, the weight of tumor in the si-LINC01314 group was noted to be increased (p < 0.05), while the OE-LINC01314, si-KLK4, and OE-LINC01314 + si-KLK4 groups displayed reductions in the weight of tumors in nude mice (p < 0.05)." (PMID 31007611, 2019). "The median H-scores of KLK2, KLK4, KLK6, and KLK14 protein expression in the nuclei of normal cells were 9, 24, 12.5, and 14.5, respectively, as compared with the tumor cells (42, 73.5, 43.5, and 62, respectively); therefore, the p values were 0.0027, 0.0009, 0.0062, and 0.0009, respectively." (PMID 35681793, 2022). "Comparison of expression profiles of ET (≤40 years) and LT (≥55 years) yielded few genes that are unique between the two groups, 7 genes B4GALNT1, S100P, KLK4, HIST3H2A, DRD4, PCSK1N, and BAPX1 were significantly overexpressed in early-onset tumours compared to late-onset tumours." (PMID 31292488, 2019). "Importantly, Western blotting and densitometry analysis showed co-expression and significantly high protein levels of both KLK4 and uPA in ascitic EOC cells (4/6) compared to cells derived from the primary tumor of these patients." (PMID 23451143, 2013). "However, there are also other forms of KLK4 which exist in the tumor microenvironment and for which there is no known function." (PMID 33255452, 2020). "In multivariable analyses, elevated KLK4 mRNA values turned out as an additional, independent predictive marker for shortened OS (p = 0.006), whereas residual tumor mass, but not ascites fluid volume, remained an independent indicator for both OS and PFS (p < 0.001 and p = 0.002, respectively)." (PMID 30811511, 2019). "Notably, in this study, we chose to focus on more advanced/bone metastatic disease when the tumor becomes resistant to AR effects, hence the choice of the PC3 cell line which also does not have endogenous KLK4 expression." (PMID 33255452, 2020).
mandible (2 papers, 2020 to 2025). "The mandible tumors that did develop in the KLK4 group were also significantly smaller based on bioluminescence and PET-CT imaging (SUVmax values)." (PMID 33255452, 2020).
benign tumors (1 paper, 2020). "The elevated expression of KLK4/KLK4 in PCa tissues compared to normal prostate or benign tumors early in disease is validated by several studies, but the correlation between its level of expression and clinical parameters in PCa progression has given contradictory results." (PMID 33255452, 2020).
neurodegenerative disease (1 paper, 2023). A disorder of the central nervous system characterized by gradual and progressive loss of neural tissue and neurologic function. "As far as we know, the plasma level of KLK4 was not reported in other neurodegenerative diseases, as well as GSN." (PMID 37194047, 2023).
KLK4 also shares sentences with these, for which no sentence is quoted: infection (6 papers); triple-negative breast carcinoma (3); benign prostatic hyperplasia (2); gastric cancer (2); bacterial diseases (1); colon adenocarcinoma (1); colorectal cancer (1); endometrial cancer (1); esophageal adenocarcinoma (1); hepatocellular carcinoma (1); male infertility (1); metastatic melanoma (1); Microcornea (1); Pancreatic Cancer (1); papillary renal cell carcinoma (1); scrub typhus (1); stomach adenocarcinoma (1); tuberculosis (1); urothelial bladder carcinoma (1); viral infection (1); Yersinia infection (1).